FOXK2 (forkhead box K2)
Diseases named in the same sentence as FOXK2 in open-access papers (continued):
Sharing a sentence is not in itself a finding about the gene and the disease.
breast invasive carcinoma (1 paper, 2024). "In contrast, FOXK2 is linked to BLCA (p < 0.05), breast invasive carcinoma (BRCA) (p < 0.05), cholangiocarcinoma (CHOL) (p < 0.05), colon adenocarcinoma (COAD) (p < 0.05), esophageal carcinoma (ESCA) (p < 0.05), and head and neck squamous cell carcinoma (head and neck squamous cell carcinoma)." (PMID 39552461, 2024).
breast tumor (1 paper, 2015). "The data from breast tumor specimens that we analyzed indicated a negative correlation between FOXK2 and ERα." (PMID 25740706, 2015).
cardiomyopathies (1 paper, 2024). "Considering that SOX9 upregulates FOXK2 expression by directly binding to the FOXK2 promoter, it is speculated that FOXK2 may play a role in SOX9-mediated cardiac fibrosis or other cardiomyopathies." (PMID 38741782, 2024).
congenital myopathy (1 paper, 2025). "In this study, we identified FOXK2 mutations in five pedigrees with congenital myopathy and ptosis through whole exome sequencing and Sanger sequencing." (PMID 40410591, 2025). "Our findings establish FOXK2 as a novel pathogenic gene in congenital myopathy associated with ptosis, highlighting its previously unrecognized role in skeletal muscle development." (PMID 40410591, 2025). "This study aims to deepen our understanding of the genetic factors involved by identifying FOXK2 [MIM:147685] as a novel pathogenic gene linked to congenital myopathy associated with ptosis." (PMID 40410591, 2025). "Our study identifies FOXK2 as a novel pathogenic gene for congenital myopathy with ptosis and highlights its essential role in skeletal muscle development and mitochondrial homeostasis, offering insights for potential diagnostics and therapies." (PMID 40410591, 2025). "In conclusion, this study identifies FOXK2 as a novel pathogenic gene for congenital myopathy associated with ptosis and reveals its previously unreported significant role in skeletal muscle development." (PMID 40410591, 2025). "In this study, we identified FOXK2 mutations with potential pathogenicity in five pedigrees with congenital myopathy associated with ptosis." (PMID 40410591, 2025). "Here, we identified FOXK2 as a novel pathogenic gene linked to congenital myopathies associated with ptosis." (PMID 40410591, 2025). "FOXK2 was identified as a novel pathogenic gene for congenital myopathy associated with ptosis and was shown to play a previously unreported, significant role in skeletal muscle development." (PMID 40410591, 2025).
COVID-19 (1 paper, 2024). A disease caused by infection with severe acute respiratory syndrome coronavirus 2. "Among these, the expression levels of FOXK2, FOXO3, and FOXP1 were found lower in the lungs of COVID-19 patients, compared to controls, thus showing the same expression levels and trends as observed for ATP2B1 (Fig. EV1G,H)." (PMID 38816514, 2024).
diabetic retinopathy (1 paper, 2025). "In diabetic retinopathy, FOXK2 has been shown to promote retinal endothelial cell migration by regulating reprogramming of glucose metabolism." (PMID 40997603, 2025). "In particular, in cases where VEGF treatment resistance exists (e.g., resistance due to VEGFR2 mutations in diabetic retinopathy), intervening in the circ-MALAT1/miR-96–5p/FOXK2 network may provide an alternative therapeutic strategy." (PMID 40997603, 2025).
invasive ductal carcinoma (1 paper, 2015). "The physiological relevance of the regulation of FOXO3a by FOXK2 is further underscored by the significant correlations between FOXO3a and FOXK2 expression in invasive ductal breast carcinoma patient samples." (PMID 26344694, 2015). "However, of all invasive ductal carcinoma patients, nuclear and total FOXK2 expression was significantly correlated with disease-specific survival (log-rank test, *P=0.048 and *P=0.049, respectively)." (PMID 26344694, 2015). "Statistical analysis of the immunohistochemical results revealed that nuclear, but not cytoplasmic or total, FOXK2 expression is marginally correlated with total FOXO3a expression (Pearson coefficient r=0.238, *P=0.054; *P⩽0.05=significant) in all the invasive ductal carcinoma cases." (PMID 26344694, 2015).
leukemia (1 paper, 2022). A malignant (clonal) hematologic disorder, involving hematopoietic stem cells and characterized by the presence of primitive or atypical myeloid or lymphoid cells in the bone marrow and the blood. "In addition, FOXK2, FOXL1, FOXO1, and FOXP3 were differentially expressed in at least six subtypes of leukemia." (PMID 36292640, 2022).
lymphoma (1 paper, 2022). A malignant (clonal) proliferation of B- lymphocytes or T- lymphocytes which involves the lymph nodes, bone marrow and/or extranodal sites. "FOXF1, FOXK2, FOXO1, FOXO3, and FOXP1 were differentially expressed in at least five subtypes of lymphoma." (PMID 36292640, 2022).
Mitochondrial myopathy (1 paper, 2025). "Our findings establish a robust model for studying mitochondrial myopathy and suggest a potential role for FOXK2 in its development." (PMID 40410591, 2025).
pneumonia (1 paper, 2024). An acute, acute and chronic, or chronic inflammation focally or diffusely affecting the lung parenchyma, caused by an infection in one or both of the lungs (by bacteria, viruses, fungi, or mycoplasma.). "To assess biological relevance of FBXO24 targeting of FOXK2, we pursued studies using Fbxo24+/− mice in a model of experimental pneumonia using K. pneumoniae." (PMID 38735474, 2024).
Pseudomonas infection (1 paper, 2024). Infections with bacteria of the genus pseudomonas. "Our findings that bacterial pathogens stimulate the turnover of FOXK2 to impact expression of downstream genes resembles findings observed in plants where the MYB30-Interacting E3 ligase targets the transcription factor MYB30 after Pseudomonas infection to affect programmed cell death." (PMID 38735474, 2024).
ptosis (1 paper, 2025). The drooping of the upper eyelid. "Additionally, we conducted rescue experiments to assess the functional impact of the FOXK2 mutation (R215W) identified in the pedigree with isolated congenital ptosis." (PMID 40410591, 2025). "Regarding the phenotype of the mice, it is important to note that while Foxk2 homozygous knockout mice showed developmental abnormalities in skeletal muscles throughout the body, including the eyelids, they did not exhibit a ptosis phenotype." (PMID 40410591, 2025).
skin melanoma (1 paper, 2024). "In addition, compared with the primary tumor sample, the expression of FOXK2 was upregulated in the metastatic sample of skin melanoma (SKCM) (p < 0.05)." (PMID 39552461, 2024).
uveal melanoma (1 paper, 2024). A melanoma derived from melanocytes of the uveal tract. "Patients with elevated levels of FOXK2 in adrenocortical carcinoma (ACC), KICH, BLCA, and uveal melanoma (UVM) have a worse prognosis than those with lower levels, as shown by both OS (p < 0.001) and DFS (p < 0.001), suggesting a negative outlook for tumor patients with high FOXK2 expression." (PMID 39552461, 2024).
tumor (33 papers, 2015 to 2025). "Through regulation of glucose and lipid metabolism, FOXK2 is closely linked to tumor initiation and progression." (PMID 38741782, 2024). "By identifying FOXK2 expression patterns, clinicians can better understand the underlying mechanisms driving tumor progression and select more personalized therapeutic approaches for patients." (PMID 38741782, 2024). "The high expression of FOXK2 is associated with Tumor size (P=0.002), T stage (P=0.001), and TNM stage (P=0.016)." (PMID 35154454, 2022). "Significant associations have been observed between FOXK2 protein expression and clinical-pathological characteristics, such as tumour size, TNM stage and vascular invasion." (PMID 30897782, 2019). "Given FOXK2’s high expression in a variety of tumors and its close association with tumor proliferation and metastasis, developing FOXK2-specific inhibitors may provide new valuable therapeutic strategies for tumor treatment." (PMID 38741782, 2024). "Importantly, we found that FOXK2 expression was significantly associated with the tumor size, T stage, and TNM stage." (PMID 35154454, 2022). "Also, FOXK2 protein expression is negatively associated with tumour grade and staining of KI-67 proliferation marker and positively correlated with favorable prognosis in both uni- and multivariate analysis." (PMID 30897782, 2019). "Also, nuclear FOXK2 has been found to be associated with tumour stage and FOXO3a expression, particularly in samples from patients receiving chemotherapy." (PMID 30897782, 2019). "Furthermore, MP treatment promoted tumor progression, reversing the inhibitory effect of FOXK2 silencing on tumor proliferation, while MI treatment markedly weakened the malignant characteristics associated with FOXK2 overexpression." (PMID 40641601, 2025). "We also identified the downstream gene FBXO32 of FOXK2 and, for the first time, found through differential expression gene enrichment analysis that it may be related to cellular ribosome‐associated pathways, thereby affecting tumor cell ribosome." (PMID 39552461, 2024). "However, FOXK2 was obviously increased in HCC and associated with tumor size, TNM stage and tumor vascular invasion, and FOXK2 upregulation in HCC cells could lead to increased cell proliferation and migration." (PMID 33313412, 2020). "Research on FOXK2’s regulation of tumor progression via metabolic pathways has primarily focused on glycolytic pathways." (PMID 40641601, 2025). "In contrast, overexpression of FOXK2 significantly exacerbated tumor malignancy and conferred a more aggressive cellular phenotype." (PMID 40641601, 2025). "In this review, we systematically describe the FOXK2 gene expression profile across distinct tumor types and discuss its potential utility as a prognostic and diagnostic molecular marker." (PMID 41959742, 2025). "The dual role of FOXK2 reveals the intricate complexity and specificity of its involvement in tumor development and progression." (PMID 38741782, 2024). "Delivering metformin and FOXK2 siRNA directly to the tumor site in the body is challenging due to the metformin's poor water solubility and the fragile nature of siRNA." (PMID 40212695, 2024). "In summary, FOXK2 emerges as a potential biomarker for certain tumors in which it plays a promoting role, indicating its utility in guiding tailored tumor treatment strategies." (PMID 38741782, 2024). "FT282-C11 cells have low expression of FOXM1, FOXM1-P (activated FOXM1), CCNB1 (canonical FOXM1 target), FOXA1, and FOXK2 (all oncoproteins), and elevated FOXO3a (a tumor suppressor), as compared to HGSOC cells, validating their utility as a normal control." (PMID 38704607, 2024). "Pan‐cancer analysis indicates that FOXK2 is differentially expressed between tumor and normal tissues." (PMID 39552461, 2024). "Examining data from eight cancer types, we discovered that FOXK2 expression levels were notably elevated in tumor cells compared to non‐tumor cells." (PMID 39552461, 2024).
tumor (continued). "Circular RNA FOXK2 aggravates PDAC tumor growth and metastasis by affecting PDXK and NUF2 expression through interaction with RNA binding protein YBX1 and hnRNPK." (PMID 38833016, 2024). "Our further research showed that FOXK2 promoted cell proliferation and migration and that FOXK2 expression was related to tumor stage and lymph node metastasis in our clinical samples." (PMID 38734828, 2024). "To determine the potential role of FOXK2 expression in tumor immunotherapy, we investigated the correlation between FOXK2 expression and some biomarkers in 33 cancer types." (PMID 39552461, 2024). "The study findings indicated a highly notable variance in FOXK2 expression levels between tumor and normal tissues across 17 types of cancer (p < 0.05)." (PMID 39552461, 2024). "The mechanism study confirmed that circ-ITCH regulated the expression of FOXK2 by adsorbing microrRNA-93-5p (miR-93-5p) to inhibit tumor growth." (PMID 36968582, 2023). "Zhang indicated that FOXK2 inhibits the malignant phenotype of ccRCC and acts as a tumor suppressor, possibly through the inhibition of EGFR." (PMID 36172141, 2022). "Several studies have revealed that ncRNAs function as tumor regulators by targeting transcription factors, including FOXK2." (PMID 36172141, 2022). "SUMOylation positively regulates FOXK2 transcriptional activity and has a role in mediating the cytotoxic response to paclitaxel through the tumour suppressor FOXO3." (PMID 36172141, 2022). "GSEA of TCGA OC samples (n = 427) also showed enrichment of UPR genes in FOXK2-high versus FOXK2-low tumor specimens." (PMID 35349489, 2022). "More importantly, increased levels of FOXK2 were found to significantly correlate with tumor size and tumor TNM stage." (PMID 35154454, 2022). "Beware of the inhibitory effect of Trichostatin A (TSA) on FOXC1 and FOXK2 expression; despite the present study confirming its tumor suppressor effect on TNBC cells, more research is needed to prove its actual roles in TNBC patients." (PMID 36292640, 2022). "More importantly, in nude mice, systemic delivery of the planned miR-602 antagomir reduces tumor growth and increases FOXK2 protein expression." (PMID 36172141, 2022). "Although FOXK2 can inhibit autophagy, tumor cells can relieve the inhibitory effect of FOXK2 on autophagy through various mechanisms to protect their malignant behavior under conditions of nutritional deficiency, radiotherapy, chemotherapy, and stress." (PMID 36172141, 2022). "In contrast, FOXK2 expression was significantly higher in PTC tissues, and 69 of the 98 tumor samples (70.4%) were positive for FOXK2 staining." (PMID 35154454, 2022). "FOXK2 was upregulated in ATC tissues, and the expression of FOXK2 was associated with tumor size, it promoted angiogenesis by inducing the transcription of VEGFA." (PMID 36172141, 2022). "Here, we provide an overview of the mechanisms underlying the regulation of FOXK2 expression and function and discuss the roles of FOXK2 in tumor pathogenesis." (PMID 36172141, 2022). "Circ-ITCH also performed tumor suppressor activity and affected the expression level of Forkhead Box K2 (FOXK2) by sponging miR-93-5p." (PMID 33841509, 2021). "More recently, growing evidence has been pointing towards a role of FOXK2 in cancer, which is likely to be context-dependent and tumour-specific." (PMID 30897782, 2019). "Despite the roles described as a tumour suppressor, a few reports have attributed an oncogenic role for FOXK2." (PMID 30897782, 2019). "Overall, there is a complicated picture emerging where FOXK2 expression may have prognostic or diagnostic value but this is likely highly tumour specific and even then, may only apply to sub-types of the particular tumour and/or to particular therapeutic regimes." (PMID 30897782, 2019).
tumor (continued). "Collectively, our results suggest that SUMOylation positively regulates FOXK2 transcriptional activity and has a role in mediating the cytotoxic response to paclitaxel through the tumour suppressor FOXO3." (PMID 29540677, 2018). "Our results also showed that MCF-7 cells overexpressing the K527/633 R mutant form of FOXK2 or the empty expression vector have lower protein and mRNA levels of its tumour suppressive transcriptional target FOXO3 compared to the wild-type FOXK2." (PMID 29540677, 2018). "Collectively, our results suggest that FOXK2 mediates the cytotoxic drug response and functions as a tumour suppressor, which is often deregulated in drug-resistant cancer cells." (PMID 26344694, 2015). "In summary, the overexpression of FOXK2 can enhance FAO metabolism in tumor cells through mechanisms that can be outlined as follows: it increases the binding affinity of FOXK2 to the mTOR, upregulates the expression of DRP1, and promotes FAO, thereby driving tumor progression." (PMID 40641601, 2025). "PHF20L1 directly inhibits a series of tumour suppressor factors, including Forkhead Box Protein K2 (FOXK2) and Hypermethylated in Cancer 1 (HIC1), through its synergistic action with the PRC2 and NuRD complexes, thereby driving glycolysis and promoting tumour occurrence." (PMID 40723918, 2025). "However, when FOXK2 was knocked down and MP treatment was administered, tumor growth markedly accelerated, and the degree of infiltration increased." (PMID 40641601, 2025). "The results showed that knockdown of FOXK2 significantly reduced tumor growth." (PMID 38734828, 2024). "This study reveals FOXK2's correlation with the tumor microenvironment in pan‐cancer." (PMID 39552461, 2024). "Additionally, forkhead box protein K2 (FOXK2), a transcription factor often found in excess in many tumors, promotes glycolysis and tumor development." (PMID 40212695, 2024). "FOXK2 plays a regulatory role in hypoxia pathway, prevalently in locally advanced solid tumors, and holds significant pathological and physiological effects in tumor progression and invasion." (PMID 38741782, 2024). "In addition, the protein interaction network of FOXK2 includes key proteins involved in pathways related to tumor occurrence and development, indicating its involvement in affecting endoplasmic reticulum protein processing." (PMID 39552461, 2024). "Of course, there are also different opinions; some people believe that high FOXK2 expression can inhibit tumor EMT and proliferation, but this may due to the heterogeneity between tumors." (PMID 39552461, 2024). "Additionally, FOXK2 exerts its tumor suppressive effects through various circRNAs that sponge miRNAs and upregulate FOXK2 expression." (PMID 38741782, 2024). "FOXK2 was highly expressed in OC and played a tumor-promoting role." (PMID 38734828, 2024). "In contrast, FOXK2 exerts tumor-suppressive functions in prostate cancer and medulloblastoma." (PMID 38735474, 2024). "The pivotal role of FOXK2 in the development of various tumors, along with its distinct expression patterns in normal and tumor tissues, suggests the potential clinical application of FOXK2 as a biomarker for the diagnosis and prognosis of different malignant tumors." (PMID 38741782, 2024). "Moreover, tail vein injection of ZrTCP@siFOXK2@CM NPs or intratumoral injections of ZrTCP@siFOXK2/Met@GelMA or ZrTCP@siFOXK2/Met@CM@GelMA effectively diminished the FOXK2 gene expression in tumor tissues." (PMID 40212695, 2024). "FOXK1 and FOXK2 display ubiquitous expression at both the RNA and protein levels to regulate cell proliferation, survival, skeletal muscle regeneration, differentiation, and tumor progression." (PMID 38735474, 2024). "Indeed, FOXK2 directly regulates the expression of nucleotide synthetic genes, promoting tumor growth and cancer cell resistance to chemotherapy." (PMID 38741782, 2024).